RNU6-174P (RNA, U6 small nuclear 174, pseudogene)
Gene: Small nuclear RNA gene on chromosome 12 (3,726,222 to 3,726,327, reverse strand). Ensembl gene ENSG00000222338.
Homologues: Orthologues: chimpanzee U6 (99% identical), macaque U6 (89% identical), dog U6 (72% identical). Paralogues in human: RNU6-1316P (81% identical), RNU6-1145P (80% identical), RNU6-20P (80% identical), RNU6-211P (80% identical), RNU6-35P (80% identical), RNU6-1152P (79% identical), RNU6-25P (79% identical), RNU6-589P (79% identical), RNU6-761P (79% identical), RNU6-820P (79% identical), RNU6-1 (78% identical), RNU6-1060P (78% identical), and 1286 more.